BCL2 (BCL2 apoptosis regulator)
Diseases named in the same sentence as BCL2 in open-access papers (continued):
Sharing a sentence is not in itself a finding about the gene and the disease.
tumor (continued). "A research found that Bcl-2 expression was not even observed in HCC tumor tissues." (PMID 35308206, 2022). "In addition, IL-3 dependent myeloid progenitor cells overexpressing BCL-2 failed to produce tumours when injected into mice." (PMID 33799592, 2021). "In comparison, in vivo study revealed that, in B16F10-tumour-bearing mice, AP/PTX-SLNs effectively suppressed tumour growth in the lungs and eliminated the cancer cells more effectively than either of the sole drug-filled SLNs through reduction of the Bcl-2/Bax fraction." (PMID 34439796, 2021). "Bcl-2 expression did not correlate with the grading of tumor." (PMID 34178320, 2021). "Overall, 30 samples (39%) showed positive BCL2 expression in tumor cells (>50%), 29 (37%) were negative and 19 (24%) were unknown." (PMID 33854591, 2021). "Sample F16 could now be classified as “double-hit” (DH) for MYC and BCL2 rearrangements, sample F67 as a MYC and BCL6 DH tumor (with partners IGH and IGL), sample F194 as MYC and BCL2 and BCL6 triple hit (TH, although MYC and BCL6 fused together) and sample F209 as TH." (PMID 34099699, 2021). "Besides blocking prosurvival BCL2 signaling in various types of malignant cells, venetoclax shows some non-canonical anti-tumor activities." (PMID 34576319, 2021). "Therefore, Bcl-2 and CCNE1 might contribute to the tumor promoting role of the NUDT21/SGPP2 pathway." (PMID 34660260, 2021). "Moreover, they suggested that Bcl-2 is playing a role in tumor genesis by inhibiting apoptotic death rather than promoting cell proliferation." (PMID 33773560, 2021). "Navitoclax (BCL-xL, BCL-2 and BCL-w antagonist) along with BCL-xL specific antagonist A-1331852, consistently primed NSCLC cells lines but venetoclax (BCL-2 antagonist) did not suggesting that it is the antagonism of BCL-xL that is priming these NSCLC tumor cells." (PMID 34315868, 2021). "Furthermore, the expression of Bcl-2 and Beclin-1 in tumor tissues was not correlated (Spearman’s correlation: p > 0.05, r = 0.047)." (PMID 34257544, 2021). "Additionally, immunohistochemical analysis indicated that SSTR2 was expressed in the tumor, but Bcl2 was not (p-Group H)." (PMID 33962620, 2021). "However, the effect of Beclin-1 expression levels on tumor cell invasiveness only appeared in combination with high Bcl-2 expression (there were no observed differences in other groups)." (PMID 34257544, 2021). "Since it has been shown by us and others that inhibition of mitochondrial metabolism primes tumor cells to apoptosis induction by BH3-mimetics, we tested whether or not interference with RAB38 enhances the cytotoxic effects of ABT263 (a Bcl-2/Bcl-xL inhibitor)." (PMID 34209035, 2021). "The BCL-2 apoptosis regulator (BCL-2) and BCL-2 like 1 (BCL-XL) proteins have been proven to be critical apoptosis inhibitors that are closely correlated with cancer chemoresistance by regulating apoptosis, proliferation, differentiation, and tumor progression." (PMID 34354046, 2021). "To determine whether Bcl-2 signaling could enhance the cytotoxicity ability of CAR-T cells at different activation stages, we used repetitive antigen stimulation to mimic in vivo long-lasting chronic tumor burden." (PMID 33429845, 2021).
tumor (continued). "Thus, our results indicate that tumor cells sensitized by sirolimus become more dependent than normal cells on BCL2 and MCL1 for sustained survival, thus increasing their susceptibility to apoptosis in the absence of these key pro-survival proteins." (PMID 34331013, 2021). "Circ_0004674 knockdown remarkably suppressed OS cell chemoresistance, proliferation, migration, invasion, OS tumor growth, and enhanced cell cycle arrest and apoptosis in vitro and in vivo through control the expression of the antiapoptotic protein MCL1, a member of the Bcl-2 gene family." (PMID 34689155, 2021). "To best of our knowledge, there is no report suggesting that the expression of SSTR2 or Bcl2 relates to tumor malignancy, and we believe that this new method may be useful for IHCC classification." (PMID 33962620, 2021). "Our data confirmed the ability of CEBPA-DT to regulate CEBPA/BCL2 expression in CDDP-resistant OSCC cells may be by a “lncRNA-mRNA” pattern, suggesting that CEBPA may be a key target of this lncRNA in the context of tumor chemoresistance." (PMID 34790046, 2021). "Furthermore, combinatorial treatment of BPP with siBcl‐2 had no obvious effect on BPP‐induced tumor suppression, indicating that Bcl‐2 was not involved in the anticancer effect of BPP in PC cells." (PMID 33226737, 2021). "Bcl-2 expression did not correlate with the grading of tumor (both WHO and Anneroth's)." (PMID 34178320, 2021). "Thus, although the tumorigenesis process may be initiated at earlier stages of B cell differentiation (see the occurrence of BCL2 translocations in FL and DLBCL), the “tumor precursor cell” undergoes its final clonal expansion in the GC." (PMID 34456919, 2021). "In the PDX models, which also showed varying BCL-2 family protein levels, while DR_MOMP predicted a differential response to ABT-199 and FOLFOX for CRC0076 and CRC0344, an n-fold greater BCL-2 concentration in one tumour did not translate to an n-fold higher requirement for BCL-2 antagonists." (PMID 33066609, 2020). "It is interesting to study the effect of a single navitoclax treatment on different cancer types with high BCL-2, BCL-XL or BCL-W expressions, and to include navitoclax in a combination treatment with other chemotherapeutic agents that have moderate anti-tumor action as well as tumor regression." (PMID 33381025, 2020). "This shift in prooxidant enzyme and antioxidant enzyme balance may cause the imbalance of proapoptotic (BAX and BAD) and antiapoptotic genes (BCL2 and BCL2L1), resulting in a tumor microenvironment which is in favor of surviving and resistant to apoptosis in Tg tumor." (PMID 33456675, 2020). "Likewise, Bcl-2, PTEN, KRAS, and BRAF are the genes that regulate apoptosis, acting as an important signaling molecule of their downstream pathway involved in the formation of tumor resistance." (PMID 32695666, 2020). "Moreover, a number of oncomirs and tumor-suppressor miRNAs are differentially regulated by CSC (microarray analyses), which could contribute to Smad3 and BCL-2 regulations." (PMID 32668597, 2020). "Compared to the control, the protein expression levels of STAT3, p-STAT3Ser727, p-STAT3Tyr705, Bcl2, cyclin D1, and c-myc were lower in the Stattic and CTS-treated groups, indicating that STAT3 might be important for tumor development and progression in TA2 SBC." (PMID 32432040, 2020). "Consequently, the F2P Score was established based on the combination of six genomic variables (ESR1, PGR, CD68, BAG1, BCL2, and GSTM1) and two clinicopathological variables (age and categorical tumor size) with the shrinkage factors of 0.314 and 0.888, respectively." (PMID 33042787, 2020). "In the analysis of relevance with clinicopathologic characteristics, the mean methylation levels of the NT5E gene were significantly higher in patients with large tumor size, high histologic grade, negative estrogen receptor expression, negative Bcl-2 expression, and premenopausal women." (PMID 33198064, 2020).
tumor (continued). "In this tumor, negative modulation of the CDX2/miR-615-5p/IGF2 axis was associated with increased tumor size and weight in animal models, as well as increased expression of tumor progression markers such as Ki-67, cyclin D1, c-MYC and Bcl-2." (PMID 32605009, 2020). "It is known that aspirin leads to cell apoptosis by inhibiting Bcl-2 expression and downregulating COX-2 expression, which is known to convert arachidonic acid to prostaglandins, and it may reduce tumor-cell invasion through the downregulation of MMP-2 expression." (PMID 32000828, 2020). "ATO can induce tumor cell differentiation, promote degradation of PML/RARα fusion protein, block specific intracellular signaling pathways, and trigger apoptosis by activating the intracellular caspase cascade, downregulating Bcl-2 expression and inhibiting NF-kB." (PMID 31632492, 2019). "After the sacrifice of the mice, the tumor xenografts were harvested and subjected to western blot analysis, which revealed an increased apoptotic response (Bax, cleaved-caspase-9 and cleaved-PARP) and the downregulation of proapoptotic proteins (Bcl-2), similar to the in vitro analysis results." (PMID 31739642, 2019). "Also, we showed that HRK-induced apoptosis could be inhibited by forced expression of Bcl-2 and Bcl-xL, suggesting the functional interaction of Bcl-2/Bcl-xL and HRK in tumor cells." (PMID 30774992, 2019). "This lack of statistically significant correlation between Bcl-2 immunohistochemical expression and prognostic parameters like tumor grade and stage, suggests that Bcl-2 immunoexpression may not be a significant prognostic marker in CRC." (PMID 31754362, 2019). "Transcriptome analysis of MCPyV-negative and MCPyV–positive MCC tumours could not detect differences in Bax and Bcl-2 levels." (PMID 31408949, 2019). "Thus, BH3-mimetics will undoubtedly be used not just to target tumours where Bcl-2 dependency is keeping them alive but to shift the apoptotic landscape to make them more primed for MOMP and thus susceptible to other treatments." (PMID 31681471, 2019). "Therefore, it was hypothesized that concomitant inhibition of BCL-2 and MDM2 would allow for an enhanced anti-leukemic effect by restoring key apoptotic and tumor suppressor pathways simultaneously." (PMID 30972300, 2019). "In summary, our results show that overexpression of FAM3B leads to increased expression of Bcl-2 and Bcl-XL, which results in the inactivation of caspases and decreases the rate of DU145 cells undergoing apoptosis, consequently promoting an increased tumor growth." (PMID 29357840, 2018). "The biochemical expression of bcl-2 and Ki67 was variable among the samples and no different trends between normal skin and tumor samples could be pointed out as confirmed by densitometric analysis and normalization for β-actin levels." (PMID 30176852, 2018). "Bcl-2 and Bax could regulate tumor cell growth by regulating cell apoptosis rather than proliferation." (PMID 30111807, 2018). "BCL-2, another important antiapoptotic protein, was abundantly present in the majority of cell lines, however, in some tumors its expression was completely lacking, independently of the tumor type." (PMID 30201866, 2018). "In this study, we found that the tumor suppressor miR-34c was inhibited by NEAT1 in OS, and restoration of miR-34c could abrogate NEAT-1-induced proliferation and inhibition of apoptosis via regulation of the balance between BCL-2 and BAX." (PMID 29654165, 2018). "However, involvement of the mRNA‐binding proteins in the modulation of Bcl‐2 expression and tumor growth by adiponectin has not been explored." (PMID 30524947, 2018). "Moreover, the ECD, which is crucial for recruiting VPS34 is necessary for inducing autophagy as well as tumor suppression, suggesting that the tumor suppressor function of BECN1 is coupled to the lipid kinase function, rather than BCL2 association." (PMID 30370269, 2018).
tumor (continued). "Bcl-2 inhibitors showed enhanced efficiacy in combination with conventional chemotherapeutic drugs (i.e., paclitaxel, 5-FU, topotecan) but with these combinations still not all of the tumor cells can be reached." (PMID 28464919, 2017). "Moreover, it was proved that FR5 treatment could inhibit tumor growth in a HCC xenograft mouse model, and immunohistochemistry results showed FR5 treatment resulted in down-regulation of Bcl-2 and YAP, and up-regulation of PTEN and PI3K." (PMID 29299170, 2017). "Taken together, BCL2 protein expression was reported to be associated with poor prognosis, however, recent studies suggested that the prognostic value of BCL2 expression is restricted to non-GCB tumor only." (PMID 28086220, 2017). "To establish whether the increased expression of pro-apoptotic BAX protein and simultaneous reduction of anti-apoptotic proteins Bcl2 and Bcl-XL in CMLD-2-treated tumor cells occurred through apoptosis, we performed western blot analysis for apoptotic proteins." (PMID 28855578, 2017). "At baseline, the molecular tumor burden was also assessed by quantitative PCR (QT-PCR) in the 28 cases with the MBR breakpoint; it was quantified in 27 of them, because in one case the BCL2/JH rearrangement resulted at the lowest limit of the test sensitivity, and thus positive but not quantifiable." (PMID 28706485, 2017). "In addition, the positive modifier of autophagy PTEN is tumor suppressive, while the negative effector BCL2 is a tumor promoter." (PMID 29262563, 2017). "The cell response to these agents is typically cytostatic allowing tumour cells to quickly adapt and acquire resistance; however, ERK1/2 inhibition increases the expression of multiple proapoptotic BOPs, thereby sensitising them to BH3‐mimetics targeting BCL‐XL and/or BCL2 or MCL1." (PMID 28548464, 2017). "LNPS@Scrambled Bcl-2 could not inhibit tumor growth as compared with normal saline treated tumor-bearing mice." (PMID 28514759, 2017). "Since some studies showed the anti-tumor effect of luteolin may be related to apoptosis, we employed FCM to determine the level of apoptosis and confirm the expression of proteins related to apoptosis, such as bcl-2, bax, caspase-9 and so forth." (PMID 28977853, 2017). "In addition, bcl-2 promotes the expression of genes necessary for angiogenesis and VEGF expression in hypoxic tumor cells, implying that bcl-2 might promote angiogenesis as well." (PMID 28977834, 2017). "A multivariate analysis showed that a HER2-positive status (OR: 6.244; 95%CI: 1.734-22.487; p=0.005), Bcl-2-negative status (OR: 0.236; 95%CI: 0.064-0.869; p=0.030) and smaller (≤2 cm) tumor sizes (OR: 0.188; 95%CI: 0.046-0.767; p=0.020) are independent predictors of pCRs." (PMID 29254147, 2017). "However, our data demonstrated that EnSCs did not affect the levels of Bax and Bcl-2 in tumor tissues obtained form SK-OV-3/EnSCs group compared with that obtained form the SK-OV-3 group." (PMID 27845405, 2016). "Hence, it is crucial to adopt at least dual BCL-2/BCL-xL BH3-mimetic (ABT-263), or even pan-BCL-2 family BH3-mimetic (obatoclax) inhibitor, in order to effectively prevent or eradicate early adaptive mitochondrially-primed tumor escape." (PMID 27852038, 2016). "However, in mice given CTX plus MAA (D1.0 and D2.0 groups), there was increased Bax expression, decreased Bcl-2 and Bcl-1 expression, increased caspase-3 expression, and slower tumor growth, but no alteration in IL-1β expression." (PMID 27043621, 2016). "Bcl-2 tested positive in a small subset of the tumor, and a TdT stain yielded a negative result." (PMID 27069035, 2016). "In this study, we showed that MGCD decreased the expression of anti-apoptotic protein Bcl-2 and increased the level of pro-apoptotic protein Bax, induced activation of caspase-3 and PARP cleavage, supporting a crucial role the mitochondrial apoptotic pathway plays in MGCD mediated tumor cell death." (PMID 27283770, 2016).
tumor (continued). "In contrast, Bcl-2 dependent xenografts responded to ABT-199 alone and had sustained complete remission (CR) to the ABT-199/cyclophosphamide combination, with one recurrent tumor maintaining Bcl-2 dependence and obtaining a second CR after a second course of therapy." (PMID 26874859, 2016). "When estimated in mice bearing AML xenograft tumor, Tf-LPN-G3139 suppressed tumor growth by approximately 60% at the end of the treatment period, which was mostly due to the antisense mechanism of G3139 to target Bcl-2 expression, as shown by the Bcl-2 immunohistochemical staining results." (PMID 27034925, 2016). "Collectively, these data suggest that miR-497 may regulate proliferation, survival and tumor vascular permeability by targeting key genes involved in DDR such as WEE1 and CHEK1, cell growth and viability such as AKT3 and BCL2 and angiogenesis regulators such as VEGFA." (PMID 26824183, 2016). "Compared with the tumor tissue from normal saline treated mice, the expression of Bax and caspase-3 were obviously up-regulated, and the expression of p-gp, MRP-1, BCRP, NF-κB and BCL-2 was remarkably down-regulated in the tumor tissue from DOX/RES-loaded NPS treated tumor-bearing mice." (PMID 27731405, 2016). "Furthermore, some of these endometrial elements within the tumor are enclosed by non-neoplastic myometrial smooth muscle that is slightly immunopositive for Bcl-2." (PMID 27491369, 2016). "Importantly, C12 inhibits tumor growth in animals regardless of either pro- or anti-apoptotic Bcl-2 proteins." (PMID 26758417, 2016). "Furthermore, Bcl-2 expression fails to influence human tumor cell apoptosis induced by the antibiotic agent Tetrocarcin-A or protein complex HAMLET." (PMID 26758417, 2016). "Additionally, Bik was independent of anti-apoptotic Bcl-2, Bcl-xL, Mcl-1 and Bcl-w suggesting a complex mechanism of tumor promotion identified by Bik high tumors." (PMID 27120789, 2016). "In addition to EMT regulation, the well-known property of miR-34a is its tumor suppressor function via inducing cell cycle arrest and apoptosis in various cancer types by targeting several molecules crucial for sustaining tumor growth such as CDK4/6, MET, HDAC1, E2F3 and Bcl-2." (PMID 25614041, 2015). "Together, these findings indicate that percutaneous injection of BIRD-2 penetrates tissue through diffusion and inhibits tumor growth without inducing immediate recognizable toxicity in mice and provide evidence of in vivo single-agent activity of targeting Bcl-2′s BH4 domain." (PMID 26317541, 2015). "The findings from immunohistochemistry analyses of tumor tissues showed that the expression of Bcl-2 was significantly reduced, while the expression of Bax was relatively increased, which suggests that the SCL induced apoptosis by shifting the Bax/Bcl-2 ratio in favor of apoptosis." (PMID 26426041, 2015). "Indeed, STAT3-dependent tumor transformation usually correlates with enhanced expression of anti-apoptotic and pro-proliferative genes such as Bcl-2, MCL-1, cyclin-D1, and c-myc, which help preventing apoptosis and stimulating tumor growth, migration, and invasion." (PMID 26106584, 2015). "Also, both miRNAs act as tumor suppressors, inhibiting the expression of proteins involved in epithelial-mesenchyme transition (EMT) and tumorigenesis, especially the transcription factor Sox5 and Bcl2." (PMID 26681200, 2015). "Our findings suggest that, after cellular exposure to HZE particles, Bcl2 may inhibit Mre11 complex-mediated DNA resection leading to suppression of the HR-mediated DSB repair in surviving cells, which may potentially contribute to tumor development." (PMID 25567982, 2015).